ROS1 (ROS proto-oncogene 1, receptor tyrosine kinase)
Description:
Receptor tyrosine kinase (RTK) that plays a role in epithelial cell differentiation and regionalization of the proximal epididymal epithelium. NELL2 is an endogenous ligand for ROS1. Upon endogenous stimulation by NELL2, ROS1 activates the intracellular signaling pathway and triggers epididymal epithelial differentiation and subsequent sperm maturation (By similarity). May activate several downstream signaling pathways related to cell differentiation, proliferation, growth and survival including the PI3 kinase-mTOR signaling pathway. Mediates the phosphorylation of PTPN11, an activator of this pathway. May also phosphorylate and activate the transcription factor STAT3 to control anchorage-independent cell growth. Mediates the phosphorylation and the activation of VAV3, a guanine nucleotide exchange factor regulating cell morphology. May activate other downstream signaling proteins including AKT1, MAPK1, MAPK3, IRS1 and PLCG2.
Synonyms: MCF3; ROS; c-ros-1
Tractability: Small molecule: an approved drug acts on it; a structure with a bound ligand is known; a high-quality ligand is known; it belongs to a druggable protein family. Antibody: UniProt places it where antibodies can reach, with high confidence; UniProt predicts a signal peptide or a membrane-spanning region; its Gene Ontology location is reachable by antibodies, with medium confidence. PROTAC: a small molecule that binds it is known.
Target class: Tyrosine protein kinase Sev family; Enzyme; TK protein kinase group; Protein Kinase; Kinase
Chemical probes: PMID24432909C8e
Gene: Protein-coding gene on chromosome 6 (117,287,353 to 117,425,942, reverse strand). Ensembl gene ENSG00000047936.
Subcellular location: Cell membrane
Subcellular location (Human Protein Atlas): Vesicles
Gene Ontology:
Molecular function: protein binding; protein phosphatase binding; protein tyrosine kinase activity; transmembrane receptor protein tyrosine kinase activity; ATP binding; protein kinase activity
Biological process: protein phosphorylation; regulation of cell growth; regulation of TOR signaling; cell differentiation; cell surface receptor protein tyrosine kinase signaling pathway; columnar/cuboidal epithelial cell development; regulation of ERK1 and ERK2 cascade; spermatogenesis; regulation of intracellular signal transduction
Cellular component: membrane; plasma membrane; receptor complex
Genetic constraint (gnomAD): Loss-of-function variants: 177 observed, 201.9 expected, observed/expected ratio (o/e) 0.88, 90% interval 0.77 to 0.99. The upper end of that interval is the gene's LOEUF score, 0.99, which puts it in group 4 of 6, group 1 being the genes least tolerant of losing a copy. Missense variants: 2,298 observed, 2,321.3 expected, observed/expected ratio (o/e) 0.99, 90% interval 0.96 to 1.02. Synonymous variants: 837 observed, 830.35 expected, observed/expected ratio (o/e) 1.01, 90% interval 0.95 to 1.07.
Cancer hallmarks: proliferative signalling (promotes)
Homologues: Orthologues: chimpanzee ROS1 (99% identical), macaque ROS1 (96% identical), pig ROS1 (86% identical), dog ROS1 (84% identical), rabbit ROS1 (83% identical), mouse Ros1 (80% identical), rat Ros1 (80% identical), tropical clawed frog ros1 (43% identical), Drosophila melanogaster sev (25% identical), zebrafish ros1 (23% identical). Paralogues in human: INSR (11% identical), IGF1R (11% identical), MET (11% identical), INSRR (10% identical), MST1R (10% identical), NTRK3 (10% identical), MERTK (10% identical), AXL (9% identical), TYRO3 (9% identical), NTRK1 (9% identical), NTRK2 (9% identical), ALK (9% identical), and 41 more.
Diseases named in the same sentence as ROS1 in open-access papers:
ROS1 is named in the same sentence as 219 diseases in open-access papers, as found by Europe PMC text mining. Sharing a sentence is not in itself a finding about the gene and the disease. The quoted sentences say what the papers report.
lung cancer (377 papers, 2011 to 2026). A malignant neoplasm involving the lung. "Ros1 (Ros1 proto‐oncogene) is a proto‐oncogene, which encodes a receptor tyrosine kinase whose aberrant fusion protein is known to cause lung cancer." (PMID 39568175, 2025). "In a case study, a 30-year-old male with an NBN germline mutation and ROS1-positive lung cancer showed improvement while receiving platinum-based chemotherapy and ROS1 inhibitors." (PMID 40429850, 2025). "ROS1, a tyrosine kinase implicated, for example, in non‐small cell lung cancer (NSCLC), has recently shown responsiveness to tyrosine kinase inhibitors." (PMID 40847660, 2025). "Third, Wt patients are a heterogeneous population that includes patients with KRAS, ALK, and ROS-1 mutation lung cancer." (PMID 36085020, 2022). "Currently, ROS1 inhibitors are widely used to treat lung cancer patients with ROS1 mutations, and there are also phase I and phase II clinical trials for ROS1 inhibitors to treat patients with other advanced or metastatic solid tumors." (PMID 36387238, 2022). "Therapies that target driver gene mutations (e.g. EGFR, ALK, ROS1) and checkpoint inhibitors such anti-PD-1 and PD-L1 immunotherapies are being used to treat lung cancer patients." (PMID 33956842, 2021). "Along the same lines, YAP1 activation was associated with poor response to treatment with the ALK/ROS1 inhibitor crizotinib in ALK-rearranged lung cancers." (PMID 34685695, 2021). "First, the number of patients with ROS1-rearranged tumors was small mainly due to the overall rarity of this mutation in lung cancer." (PMID 33005033, 2020). "In the present study, we expanded the detection range to include mutations of 59 common cancer-associated genes and fusions of ALK and ROS1, and only a few classic lung cancer GA were observed." (PMID 31387567, 2019). "Third, lung cancers harboring minor EGFR mutations, which are considered to be refractory to EGFR - TKI, were included in Mt, whereas lung cancers harboring anaplastic lymphoma kinase genes or ROS-1 gene mutations were included in Wt." (PMID 30290774, 2018). "Specific tyrosine kinase inhibitors have shown remarkable clinical response in patients with tumors characterized by RTK activation, such as gefitinib and erlotinib in EGFR-mutated and crizotinib in ALK- or ROS1-rearranged lung cancer." (PMID 29755689, 2018). "Somatic alterations of ROS1 have previously been detected in lung cancer and glioblastoma, and we found ROS1 mutations in a small fraction of HD-ALL patients." (PMID 27683039, 2016). "Recently, novel ROS1 mutations in lung cancer cell lines as well as epithelial-to-mesenchymal transition have been described to confer resistance to crizotinib." (PMID 26018876, 2015). "ROS1 gene mutations occurred more frequently in our study compared with the overall lung cancer patient population." (PMID 26332764, 2015). "ROS1-rearranged lung cancer is considered to have a high risk of thrombosis." (PMID 39559635, 2024). "Therefore, Lin and co-authors studied mechanisms of resistance to crizotinib and lorlatinib in ROS1 fusion-positive lung cancer by structural modeling and comparison of wild and mutated 3D structures of ROS1 (ROS proto-oncogene 1, receptor tyrosine kinase)." (PMID 37763211, 2023). "Molecular characterization has led to the definition of new subgroups such as lung cancer mutated for epidermal growth factor receptor, lung cancer rearranged for analytic lymphoma kinase and ROS1 kinase domain, and PDL1 expression, which need specific treatments and strategies." (PMID 35685154, 2022). "Wild-type ROS1 activation has been implicated in the mesenchymal-to-epithelial transition and in cellular differentiation during the development of kidney, lung, small intestine, heart, and lung cancer." (PMID 33435440, 2021).
lung cancer (continued). "In this review, we briefly introduce the biology and role of ROS1 in lung cancer and discuss the underlying acquired mechanisms of resistance to crizotinib and the promising new agents able to overcome resistance mechanisms and offer alternative efficient therapies." (PMID 33172113, 2020). "Alternatively, the differential rate of acquiring or eliminating EGFR, ALK, or ROS1 lung cancer somatic mutations may be also influenced by the inheritance of the EGLN1D4E/C127S variant which modulates HIFs-stability." (PMID 28036300, 2017). "However, most of these clinical studies reporting on the inhibitor resistance mechanisms of ROS1-rearranged lung cancer were conducted with only limited samples, and only a few explored the association between treatment-emergent ROS1 point mutations and patterns of disease progression." (PMID 35361870, 2022). "As a corollary, the same general diagnostic approach using a suite of novel SMART kits could also be equally applied to target and detect clinically significant RET and ROS1 fusions that are associated with the disease progression of other types of lung cancers." (PMID 27409166, 2016). "ROS1 immunohistochemistry (IHC) is often used for screening of lung carcinomas for ROS1 gene rearrangement and has a cytoplasmic and/or membranous staining pattern." (PMID 42254076, 2026). "ROS1‐fusion gene positive (ROS1+) non‐small cell lung cancer (NSCLC) accounts for ~2% of newly stage IV NSCLC adenocarcinoma patients." (PMID 40878657, 2025). "It was first reported in NSCLC in 2007 and after that, ROS1 became an established therapeutic target of lung cancer." (PMID 39998561, 2025). "This discovery provides a new therapeutic option for the treatment of patients with ROS1- or ALK-positive lung cancer." (PMID 40584293, 2025). "The correlation between TEs and oncogenic drivers in lung cancer is not well understood yet, necessitating further investigation, particularly concerning the elevated risks of TEs in patients with ROS1 and ALK rearrangements." (PMID 40751559, 2025). "Crizotinib, an anaplastic lymphoma kinase (ALK)/ROS1/c‐MET inhibitor, improves outcomes in ALK‐positive non‐small cell lung cancer (NSCLC) but can cause crizotinib‐associated renal cysts (CARCs), a rare yet clinically relevant adverse effect." (PMID 40542555, 2025). "It should be noted that we have followed a standardized methodology (ordinal assessment of ROS1 expression) which has been consistently correlated with the presence of ROS1 fusions in lung cancer." (PMID 40847660, 2025). "Currently, some studies have reported an association between lung cancers with ALK and ROS1 rearrangements and an elevated risk of TEs." (PMID 40751559, 2025). "The first drugs developed for ROS1-positive lung cancer, such as crizotinib, were effective but showed limitations over time, particularly with brain involvement and resistance." (PMID 41294688, 2025). "Originally developed as an ALK and ROS1 inhibitor for the treatment of non‐small cell lung cancer (NSCLC), the newfound ability of crizotinib to inhibit CD147 and MCT1 extends its therapeutic potential into the realm of cancer metabolic reprogramming." (PMID 40692663, 2025). "The International Association for the Study of Lung Cancer recommends, at a minimum, testing for EGFR, ALK, and ROS1." (PMID 41153394, 2025). "The challenge remains in subtypes of lung cancer patients that harbor driver mutations like EGFR, ALK, and ROS1 mutations." (PMID 39932765, 2025).
lung cancer (continued). "Of the remaining 493 LUAD cases, the three studies showed no fusions involving any of the recurrent genes, while SplitFusion detected two cases with SLC34A2::ROS1 fusion, an indication for ROS1-targeted therapy in lung cancer patients." (PMID 40041857, 2025). "For instance, capturing ALK or ROS1 fusion breakpoints in EV-DNA from lung cancer patients allow identification of candidates for ALK/ROS1 inhibitors even when tissue biopsy is infeasible." (PMID 41301080, 2025). "Among ROS1-positive lung cancers, we also observed that CD74::ROS1 tumors had more fusion subclones than ROS1 tumors with other fusion partners." (PMID 40041857, 2025). "Tobacco is a major carcinogen linked to lung cancer, but other genetic triggers, particularly mutations in KRAS, EGFR, ALK, BRAF, RET, MET and ROS1, are also central to its development." (PMID 40556802, 2025). "Lyer et al32 discovered that the expression level of the MYC gene was significantly up-regulated in ROS1 fusion-positive lung cancer cells after long-term use of TKIs." (PMID 40584293, 2025). "In our study, we also found that ACACA expression is related to mutations of common driver genes in NSCLC, which agrees with recent research that common driver gene mutations in lung cancer, such as KRAS, EGFR, ROS1 and ALK, are closely related to metabolism." (PMID 41169354, 2025). "Clinical outcomes in ROS1‐fusion positive (ROS1+) non‐small cell lung cancer (NSCLC) by fusion partner and resistance mechanisms are limited." (PMID 40878657, 2025). "ROS1 inhibitors play a critical role in the treatment of ROS1 fusion–positive non–small cell lung cancer (NSCLC)." (PMID 41586108, 2025). "Although only 1%–2% of lung cancer patients are found to carry the ROS1 fusion gene, there is still a significant number of patients with the disease." (PMID 40584293, 2025). "Research has found an interesting phenomenon: in lung cancer patients under 50 years old, there is a higher proportion of lung cancer with targetable genomic changes, such as EGFR mutations, ALK or ROS1 fusions, or ERBB2 insertions." (PMID 38756780, 2024). "Previous study has shown that treatment of lung cancer harboring ROS1 fusion with lorlatinib can activate YAP1 in vivo or in vitro." (PMID 38499647, 2024). "The present case is an extremely rare case of ROS1-rearranged lung cancer with cardiac tamponade as an initial manifestation." (PMID 39559635, 2024). "The 2018 CAP/AMP/IASLC (College of American Pathologists/Association of Molecular Pathology/International Association for the Study of Lung Cancer) guidelines advocated testing for EGFR, ALK, ROS1, and BRAF upfront." (PMID 39834530, 2024). "•Genetic alterations in ROS1 can lead to the expression of oncogenic fusion proteins in multiple tumor types, including in 1% to 2% of non–small-cell lung cancer (NSCLC) cases." (PMID 38245456, 2024). "A study in which WES of primary lung–BrM pairs was carried out showed that BrMs exhibited higher somatic variants and chromosomal alterations than primary lung cancers, particularly in genes associated with lung cancer (e.g., KRAS, ROS1, and STK11)." (PMID 39593114, 2024). "In lung cancer, two ROS1 fusion transcripts, namely, SLC34A2-ROS1 and CD74-ROS1, were initially identified as proto-oncogenes." (PMID 38472960, 2024). "Currently, there are FDA-approved targeted therapies for lung cancers with mutations and genomic alterations in EGFR, ALK, ROS-1, NTRK, MET, RET, HER2, and BRAF." (PMID 39272844, 2024). "ROS1 IHC can be performed using cellular specimens, paraffin‐embedded tissue specimens, and cell blocks for lung cancer detection." (PMID 38629293, 2024). "Recently, it has been shown that the ALK and ROS1 genes driving lung cancer are also present in colorectal cancer." (PMID 38770671, 2024). "ROS proto-oncogene 1 (ROS1) rearrangements, found in 1% to 2% of patients with non–small-cell lung cancer (NSCLC), can result in the expression of oncogenic fusion proteins in different tumor types." (PMID 38245456, 2024).
lung cancer (continued). "TMEM106B::ROS1 has previously been found in non–small cell lung cancer, and the resulting fusion protein contains a ROS1 tyrosine kinase domain with assumed oncogenic activity." (PMID 38877653, 2024). "In Japan, ROS1 fusion gene testing has been covered by insurance since 2017, and BRAF V600E mutation testing since 2018, but they were hardly investigated in lung cancer cases from 2008 to 2014 when our patients were enrolled." (PMID 39539600, 2024). "ROS1 gene fusions are an established oncogenic driver comprising 1%-2% of non–small cell lung cancer (NSCLC)." (PMID 39177972, 2024). "We believe that our study makes a significant contribution to the literature because our review revealed the following findings: the proto‐oncogene ROS1 is mostly expressed in malignant tumours, such as non‐small cell lung cancer (NSCLC)." (PMID 38629293, 2024). "The biopsy specimen was analyzed using the AmoyDx® Pan Lung Cancer PCR Panel, which detected ROS1 fusions." (PMID 39391406, 2024). "Common genetic mutations in lung carcinoma include EGFR, KRAS, EML4-ALK, Ros1, and c-MET, among others." (PMID 38571504, 2024). "Here, we report a case of ROS1-rearranged lung cancer overexpressing MET protein at baseline, which then acquired genomic amplification of MET as an off-target mechanism of resistance to ROS1 inhibitors." (PMID 37923925, 2023). "With the development of biomarkers, the treatment of lung cancer has also evolved with the introduction of several lines of TKIs in patients with EGFR, ALK, ROS1, and NTRK mutations." (PMID 37371816, 2023). "Entrectinib is an effective drug for treating solid tumors with NTRK gene rearrangement and non‐small cell lung cancer (NSCLC) with ROS1 gene rearrangement." (PMID 36416133, 2023). "Non-small cell lung cancer (NSCLC), a sub-type of lung cancer, is frequently associated with activating mutations in receptor tyrosine kinases, including EGFR, MET, ALK, and ROS1, which disrupt tyrosine kinase signaling and drive cancer progression." (PMID 36996232, 2023). "Patients with metastatic ROS1-rearranged lung cancers typically derive substantial benefit from ROS1-targeted tyrosine kinase inhibitors (TKIs) such as crizotinib and entrectinib, often with marked initial tumor responses." (PMID 37923925, 2023). "This retrospective study aimed to determine the prevalence of ROS1 fusion in a cohort of Norwegian, early-stage resectable lung cancer." (PMID 37237384, 2023). "The International Association for the Study of Lung Cancer (IASLC) recommends to test EGFR mutations and ALK and ROS1 fusions." (PMID 36899890, 2023). "Two previous studies on early-stage lung cancer found a prevalence of ROS1 fusion of 0.4–1.2% in adenocarcinomas." (PMID 37237384, 2023). "This implies that ROS1 fusions in early stage lung cancer can be a target for neoadjuvant or adjuvant therapy in the future." (PMID 37237384, 2023). "As our understanding of the molecular biology of lung cancer increases, many mutated targets are being identified, including the epidermal growth factor receptor (EGFR), anaplastic lymphoma kinase, ROS1, BRAF V600E mutation, etc." (PMID 36716088, 2023). "We constructed a CCCN and CFN from measurements of phosphorylation, acetylation, and ubiquitination in 10 different lung cancer cell lines with driver mutations in EGFR, ALK, ERBB2/HER2, ROS1, and DDR2, treated with four different TKIs." (PMID 36996232, 2023). "Precision therapy with oncogene-targeted drugs has dramatically changed the outcomes for lung cancer patients with tumors positive for mutated EGFR or fusion kinases including ALK and ROS1 and others." (PMID 36845684, 2023). "ROS proto‐oncogene 1, receptor tyrosine kinase (ROS1) rearrangements are a crucial therapeutic target in non‐small cell lung cancer (NSCLC)." (PMID 37584407, 2023). "In the present study, we investigated the prevalence of ROS1 fusion in a Norwegian cohort of early-stage lung cancer." (PMID 37237384, 2023).